PIK3CD (phosphatidylinositol-4,5-bisphosphate 3-kinase catalytic subunit delta)
Diseases named in the same sentence as PIK3CD in open-access papers (continued):
Sharing a sentence is not in itself a finding about the gene and the disease.
primary immunodeficiency (23 papers, 2018 to 2025). "Activated PI3K delta syndrome (APDS) is a rare primary immunodeficiency caused by gain-of-function (GOF) mutations in PIK3CD or PIK3R1, leading to immune dysregulation." (PMID 40951253, 2025). "Activated phosphoinositide 3-kinase delta syndrome (APDS) is a primary immunodeficiency caused by gain-of-function mutations in the PIK3CD gene, leading to dysregulated immune responses." (PMID 41019061, 2025). "Activated PI3 kinase delta syndrome (APDS) is a rare, inherited primary immunodeficiency characterized by gain-of-function mutations in the PIK3CD or PIK3R1 genes, resulting in hyperactivation of the PI3Kδ pathway and consequent immune dysregulation." (PMID 40978950, 2025). "Germline heterozygous gain-of-function (GOF) mutations in the PIK3CD gene lead to a rare primary immunodeficiency disease known as activated phosphoinositide 3-kinase (PI3K) δ syndrome type 1(APDS1)." (PMID 38287413, 2024). "Following the description of two cohorts of patients with an inboirn error of immunity (also known as primary immunodeficiency) with gain-of-function variants in the PIK3CD gene a decade ago, the disease entity activated PI3K delta syndrome (APDS) was named." (PMID 39679264, 2024). "APDS is a primary immunodeficiency resulting from increased activity of the class IA PI3Kd isoform that is caused by mutations in the PIK3CD gene product p110d (APDS1) or in the gene encoding the PI3Kd regulatory subunit p85α (APDS2)." (PMID 38364889, 2024). "Recent studies have identified mutations in the PIK3CD gene, which encodes the p110δ catalytic subunit, in patients with primary immunodeficiencies." (PMID 35799777, 2022). "Patients with gain-of-function mutations in PIK3CD, which encodes p110δ, exhibit a primary immunodeficiency, activated PI3Kδ syndrome (APDS), characterized by lymphopenia, lymphoproliferation, and recurrent respiratory infections." (PMID 34644563, 2021). "Recently, a primary immunodeficiency caused by mutations in the PIK3CD or PIK3R1 genes (encoding p110δ and p85α, respectively) was reported and called activated PI3K delta syndrome (APDS)." (PMID 32218789, 2020). "Mutations in the PIK3R1 and PIK3CD genes can lead to activated phosphoinositide 3-kinase δ syndrome (APDS), a primary immunodeficiency affecting both humoral and cellular immunity, with some phenotypic similarities to CVID." (PMID 38028622, 2023). "WES revealed heterogeneous genetic background among CVID patients with tumors, identifying gene variants associated with primary immunodeficiencies (such as CTLA4, PIK3CD, PMS2) and/or increased cancer susceptibility (including BRCA1, RABEP1, EP300, KDM5A)." (PMID 30723478, 2018).
lymphoma (22 papers, 2014 to 2026). A malignant (clonal) proliferation of B- lymphocytes or T- lymphocytes which involves the lymph nodes, bone marrow and/or extranodal sites. "IOA-244 inhibits the in vitro growth of lymphoma cells and its activity correlates with the expression levels of PIK3CD, suggesting cancer cell–intrinsic effects of IOA-244." (PMID 37066023, 2023). "In contrast, the divergence in expression observed for GSK3B and PIK3CD between lymphomas and cell lines is likely due to clonal selection or cultivation induced artifacts, hence limiting the value of the cell lines as drug testing system." (PMID 29674676, 2018). "A previous study addressing the genetic cause of CVID in 10 patients with lymphoma revealed a heterogeneous genetic background, including a patient with CTLA4-insufficiency and one with APDS as a consequence of a monoallelic gain-of-function variant in PIK3CD." (PMID 35250968, 2022). "In addition, PIK3CD and SPI1 were also related to different types of lymphoma." (PMID 33785011, 2021).
glioblastoma (20 papers, 2011 to 2025). The most malignant astrocytic tumor (WHO grade IV). "In glioblastomas and colorectal cancers, PIK3CD is reported to be upregulated and promote cell growth, migration, and invasion through the activation of Akt signaling." (PMID 32555190, 2020). "While PIK3CD/p110δ has been well studied in blood cancers, little is known about the role of this subunit in glioblastoma." (PMID 29326882, 2017). "Our results suggest that PIK3CD/p110δ plays a dispensable role in the disease progression of glioblastoma." (PMID 29326882, 2017). "We have probed different glioblastoma cells with a PIK3CD/p110δ antibody." (PMID 29326882, 2017). "Nonetheless, the role of this subunit in glioblastoma and whether targeting PIK3CD/p110δ is an effective treatment for glioblastoma require further research." (PMID 29326882, 2017). "In addition, the tumor suppressive role of miR-663a was demonstrated in colorectal cancer cells, prostate cancer and especially in glioblastoma, in which miR-663a targeted PIK3CD and served as a prognostic biomarker." (PMID 27184257, 2016). "Additionally, the PI3K catalytic subunit p110δ (i.e., PIK3CD) was directly regulated by miR-30b or miR-663 in human colorectal cancer and glioblastoma cells, respectively." (PMID 25893379, 2015). "Indeed, the amplification of PIK3CD gene is more enriched in glioblastoma." (PMID 38336976, 2024). "Genes such as VEGFA, PD-L1, PIK3CD, PRMT5, and STAT3 emerge as central nodes driving glioblastoma progression and therapeutic resistance." (PMID 41179304, 2025). "Similar findings were also reported that miR-663 acted as a tumor suppressor in glioblastoma by targeting CXCR4 and PIK3CD." (PMID 27667893, 2016). "Overexpression of p110δ mRNA and increased copy number of the PIK3CD gene were found in some cases of glioblastoma." (PMID 23459844, 2013). "Together, these results suggest that PIK3CD/p110δ regulates the migration, but not the survival, of glioblastoma cells." (PMID 29326882, 2017).
asthma (15 papers, 2007 to 2024). "An inhaled PI3Kδ inhibitor is currently in early clinical trials for activated PI3K delta syndrome (APDS) caused by gain of function mutations in PIK3CD, with the intent of expanding into both asthma and COPD indications." (PMID 28596972, 2017). "However, an inhaled PI3Kδ inhibitor is currently in early clinical trials for primary immune deficiency, activated PI3K-delta syndrome (APDS) caused by gain of function mutations in PIK3CD, and progressing into both asthma and COPD indications (NCT02294734, ClinicalTrials.gov)." (PMID 28596972, 2017). "Among the up-regulated genes were 3 associated with inhibition of proliferation (Gpnmb, Setd8, Runx2) and 1 promoting inflammatory and immune responses (Pik3cd), as well as 4 asthma-related genes (Arg1, Ccl24, Slc7a2, Mcpt1) identifiable only through qRT-PCR." (PMID 18087596, 2007). "However, the few asthma/inflammatory genes that are differentially expressed (Pik3cd, Arg1, Slc7a2, Ccl24, Mcpt1) are all up-regulated in ETS-exposed mice." (PMID 18087596, 2007). "In particular, seven gene targets (HMGCR, ADORA1, IL6R, CD86, BCR, PIK3CD, and NOS1) are prioritized for asthma drug repurposing." (PMID 35052792, 2022).
colorectal cancer (15 papers, 2014 to 2023). A primary or metastatic malignant neoplasm that affects the colon or rectum. "However, several epithelial malignancies have also been shown to express p110δ, and 3% of patients with head and neck, germ cell, or colorectal cancer are reported to carry a PIK3CD mutation." (PMID 32630372, 2020). "PIK3CD significantly boosted colorectal cancer cell motility, invasion, and proliferation in vitro, as well as tumor development in vivo." (PMID 37861728, 2023). "It has been reported that miR-30a might function as a metastasis suppressor by downregulating phosphatidylinositol-4,5-bisphosphate 3-kinase catalytic subunit delta (PIK3CD) in colorectal carcinoma to suppresses cell migration and invasion." (PMID 27790245, 2016). "Reports show that miR-30b-5p inhibits human colorectal cancer by targeting KRAS, PIK3CD and BCL2 and modulates glioma cell proliferation by directly targeting MTDH." (PMID 32586272, 2020). "In this study, we demonstrated frequent methylation of the ErbB signalling network (PIK3CD, PKCΒ, ERBB4, PAK7) in colorectal cancer (CRC)." (PMID 25366420, 2015).
Lymphadenopathy (15 papers, 2017 to 2023). Enlargement (swelling) of a lymph node. "Patients with APDS have a gain of function mutation in the gene encoding PI3Kδ (PIK3CD) and present with recurrent bacterial and herpesvirus sinopulmonary infections, lymphadenopathy, and autoimmune/inflammatory manifestations." (PMID 31546615, 2019).
prostate carcinoma (15 papers, 2010 to 2025). A carcinoma that arises from epithelial cells of the prostate gland. "In patients with prostate cancer, PIK3CD mutation and amplification are infrequent events (≤1.1%)." (PMID 32630372, 2020). "It has been shown that alternative splicing and overexpression of PIK3CD promote tumor aggressiveness and drug resistance in African American prostate cancer patients." (PMID 34316327, 2021). "The authors examined the association between several SNPs in PI3Ks genes (PIK3CD, PIK3C2A, PIK3R3, PIK3AP1, and PIK3C2B) and prostate cancer risk: among the five genes, only PIK3C2B showed a cluster of SNPs related to prostate cancer risk." (PMID 23658859, 2013). "Specific splice variants of PIK3CD, TSC2, and RASGRP2 are associated with a more aggressive oncogenic phenotype in AA prostate cancer cells, which has been hypothesized as an underlying mechanism for prostate cancer health disparities between AA and EA men." (PMID 30463359, 2018). "The four miRNAs regulate PTEN expression post-transcriptionally, and affect the downstream PI3K/Akt pathway via PIK3CA (p110α), PIK3CD (p110δ), PIK3R1 (p85), Akt as well as cyclin D1, thus promote prostate cancer cell proliferation in vitro." (PMID 24098737, 2013). "Finally, the “prostate cancer” pathway also includes DEGsSD that are relatively specific to the (human) prostate (SRD5A2, KLK2, NKX3-1 and CREB3L4), proto-oncogenes (EGFR, PDGFRA, PDGFRB, NRAS) and druggable candidates (PIK3CD, CTNNB1, PIK3CG, CDKN1A)." (PMID 34768937, 2021). "The “prostate cancer” pathway also comprises genes that are relatively specific to the (human) prostate (CREB3L4, KLK2, NKX3-1 and SRD5A2), proto-oncogenes (EGFR, NRAS, PDGFRA and PDGFRB), and druggable candidates (CDKN1A, CTNNB1, EGFR, NRAS, PDGFRA, PDGFRB, PIK3CD and PIK3CG)." (PMID 34768937, 2021). "However, a PIK3CD splice variant missing exon 20 (PIK3CD-S) has been identified in African American prostate cancer patients that can promote proliferation and AKT-mTOR signaling, and several CRPC cell lines have been shown to express p110δ at high levels, comparable to that detected in leukocytes." (PMID 32630372, 2020).
acute myeloid leukemia (14 papers, 2010 to 2022). Acute myeloid leukemia (AML) is a group of neoplasms arising from precursor cells committed to the myeloid cell-line differentiation. "In acute myeloid leukemia cells, PIK3CD is the only class I PI3K isoform that consistently is detected." (PMID 23259526, 2012). "In addition, PIK3CD has also emerged as a key therapeutic target for haematological malignancies, notably acute myeloid leukaemia (AML)." (PMID 22876838, 2012).
schizophrenia (13 papers, 2014 to 2023). A major psychotic disorder characterized by abnormalities in the perception or expression of reality. "PIK3CD encodes phosphoinositide 3-kinases (PI3Ks) that are involved in the immune response and are associated with neurodevelopmental disorders, including schizophrenia." (PMID 37383091, 2023). "In addition, we found downregulation of PIK3CD, also previously associated with schizophrenia." (PMID 31959813, 2020). "PIK3CD (FC = 1.26, p = 0.005) encodes the phosphoinositide 3-kinase catalytic subunit which is a kinase in the PKA pathway associated with schizophrenia and neurologically compromised brains." (PMID 33964983, 2021). "Studies are underway investigating such factors in the context of PIK3CD overexpression, as it relates specifically to schizophrenia." (PMID 32180704, 2020). "One study in 2012, provides evidence for link between the NRG1-ErbB4 signaling pathway and PIK3CD in schizophrenia." (PMID 31959813, 2020). "Although the expression pattern of human PIK3CD follows a similar distribution as in mice (Allen Human Brain Atlas (2010)), reports of its non-immunological functions are scarce, with only a few studies implicating this isoform in schizophrenia and autism." (PMID 34786564, 2021). "Thus, in human brains and in lymphoblastoid B-cell lines (LCLs) of subjects with schizophrenia, an ErbB4 risk haplotype (AGG; rs7598440, rs839523, rs707284) was found to be associated with elevated ErbB4 CYT-1 transcription and consequently raised expression of PIK3CD (p110δ)." (PMID 26877878, 2016).
leukemia (12 papers, 2009 to 2024). A malignant (clonal) hematologic disorder, involving hematopoietic stem cells and characterized by the presence of primitive or atypical myeloid or lymphoid cells in the bone marrow and the blood. "Another example of the gene network architecture of leukemia emerges by tracking up- and downstream interconnections of the genes PIK3CG (DEG-DMG) and PIK3CD (a DMG network hub) from the PI3K/AKT signaling pathway (enriched in the set of DEG-DMGs)." (PMID 32034170, 2020).
colon carcinoma (11 papers, 2012 to 2024). "Other important molecules connecting CRC-associated pathways include PIK3CD, which normally upregulates protein kinase B, glycogen synthase kinase 3β and β‐catenin and, thus, colon cancer growth and proliferation." (PMID 39478120, 2024). "Overexpression of the PIK3CD gene has been associated with cell proliferation in colon cancer and is responsible for poor prognosis among patients." (PMID 34068918, 2021). "Cytolytic-high colon tumors on the other hand, were characterized by recurrent deletions at loci 1p35.3 (PIK3CD, TP73, miR34a), 6p25.3 (FOXC1), and 21q11.1 (Let-7c), and amplifications at loci 8q24.21 (MYC) and 20q13.12 (MMP9)." (PMID 31429779, 2019). "MALAT1 is also increased in colon cancer cells, directly binding to miR-663a, thus acting as a competing endogenous lncRNA; as a result, important cancer-related miR-663a targets (TGFB1, PIK3CD, P21, JunB, and JunD) were affected." (PMID 32183400, 2020). "Notably, upon analysis of bulk RNA in the 32 colon cancer patient samples, we found that ciRS-7 was significantly positively correlated with FOS (r = 0.84, P < 0.0001), NR4A3 (r = 0.80, P < 0.0001) and PIK3CD (r = 0.40, P = 0.02)." (PMID 32917870, 2020). "At the same time, PIK3CD is expressed to moderate degree in certain neoplastic cells of non-leukocyte origin, such as melanoma cells, breast and colon cancer cells." (PMID 23259526, 2012).
agammaglobulinemia (10 papers, 2020 to 2025). A decreased level of serum immunoglobulins. "Similarly, bi-allelic LOF mutations in PIK3CD are now known to cause B cell deficiency and agammaglobulinemia, which is quite distinct from the immune dysregulated state of individuals with monoallelic activating PIK3CD mutations." (PMID 31953710, 2020). "A similar clinical phenotype of agammaglobulinemia or hypogammaglobulinemia is observed in patients with hemizygous variants in BTK, biallelic variants in BLNK, heterozygous gain-of-function (GOF) PIK3CD, or loss-of-function (LOF) PIK3R1 variants, which all encode proteins involved in BCR signaling." (PMID 41607487, 2025). "The most frequent main genetic causes of predominantly antibody deficiencies in children infected with SARS-CoV-2 were BTK (n = 41), NFKB2 (n = 4), TNFRSF13B (n = 3), PIK3CD (n = 3), and PIK3R1 (n = 2)." (PMID 37559153, 2023). "Patients with a conclusive diagnosis from the antibody deficiency category were diagnosed with activated PI3K-delta syndrome (APDS1) (n=2/5; 40%), X-linked agammaglobulinemia (XLA) (n=2/5; 40%) and AID deficiency (n=1/5; 20%), based on pathogenic variants in PIK3CD, BTK and AICDA, respectively." (PMID 34992599, 2021). "In view of this patient’s clinical presentation and agammaglobulinemia, the differential diagnosis includes autosomal recessive forms of the disease (such as defects in IGHM, IGLL1, CD79A/B, PIK3R1, PIK3CD), as well as, more rarely, XLA." (PMID 41327272, 2025).
melanoma (10 papers, 2009 to 2025). A malignant, usually aggressive tumor composed of atypical, neoplastic melanocytes. "Five genes (CXCL10, TNF, PIK3CD, PIK3R2, and CXCL1) of the TNF signalling pathway and seven genes (CXCL9, GDF15, BMP7, TNFRSF15, CXCL10, TNF, and CXCL1) of the cytokine–cytokine receptor pathway were commonly upregulated in melanoma cells." (PMID 39496484, 2024). "Although the related gene set size did not allow to reach significance, the melanoma canonical pathway included two of them, namely PIK3CD and EP300." (PMID 34067022, 2021).
autoimmune disease (9 papers, 2012 to 2023). A disorder resulting from loss of function or tissue destruction of an organ or multiple organs, arising from humoral or cellular immune responses of the individual to their own tissue constituents. "Furthermore, the contribution of PIK3CD subunit in other autoimmune disorders, like rheumatoid arthritis has also been confirmed and PIK3CD is a promising therapeutic target in this disease because of its role to leukocyte biology." (PMID 23259526, 2012).
colitis (8 papers, 2007 to 2024). Inflammation of the colon. "Fam76b knockout reduced the stability of PIK3CD mRNA, then regulated the PI3K/Akt/NF-κB pathway, promoted M1 macrophage polarization, and led to Fam76b knockout mice being susceptible to DSS-induced experimental colitis." (PMID 38421448, 2024). "In humans, the PI3Kδ gene (PIK3CD) maps to the IBD7 susceptibility locus on chromosome 1p36, while the PI3Kδ-inhibitor Idelalisib, a therapeutic agent for certain tumors, can cause colitis as a side effect." (PMID 31546615, 2019).
hepatocellular carcinoma (8 papers, 2018 to 2025). A malignant tumor that arises from hepatocytes. "PIK3CD has been implicated in the progression of various solid tumors, including colorectal, breast, and hepatocellular carcinoma, with its role in tumor growth and treatment resistance offering avenues for therapeutic interventions." (PMID 39204124, 2024). "Three of them (i.e., Pik3cd, Klf4, Hoxb5) were excluded through analysis of their expression in hepatoma cells transfected with the sja-miR-7-5p mimics." (PMID 30967999, 2019). "It has been demonstrated that miR-7 can inhibit cancer progression by suppressing CCNE1 and PIK3CD in hepatocellular carcinoma (HCC)." (PMID 30126353, 2018). "At present, limited studies on PIK3CD, HRAS, E2F2, BIGF1, WNT4, and VAV3 genes have been reported in hepatoma cells, indicating the need for further research." (PMID 33959508, 2021). "The results of target prediction showed that PDGFRA, FLT1, PIK3CD and MET might be the main targets of compound 15 against hepatocellular carcinoma." (PMID 41023382, 2025).
Autoimmunity (7 papers, 2016 to 2023). The occurrence of an immune reaction against the organism's own cells or tissues. "Of note, the loss-of-function mutations in PIK3R1 and PTEN lead to a similar clinical phenotype to that of GOF mutations in the PIK3CD gene, characterized by decreased B lymphocytes and naïve T lymphocytes, lymphoproliferation, and autoimmunity." (PMID 35990641, 2022).